CCDC28A (coiled-coil domain containing 28A)
Synonyms: C6orf80; CCRL1AP; DKFZp586D0623; LTAP2A
Gene: Protein-coding gene on chromosome 6 (138,773,493 to 138,793,319, forward strand). Ensembl gene ENSG00000024862.
Subcellular location (Human Protein Atlas): Plasma membrane; Nucleoplasm
Genetic constraint (gnomAD): Loss-of-function variants: 10 observed, 10.22 expected, observed/expected ratio (o/e) 0.98, 90% interval 0.6 to 1.63. The upper end of that interval is the gene's LOEUF score, 1.63, which puts it in group 6 of 6, group 1 being the genes least tolerant of losing a copy. Missense variants: 96 observed, 126.23 expected, observed/expected ratio (o/e) 0.76, 90% interval 0.64 to 0.9. Synonymous variants: 47 observed, 46.81 expected, observed/expected ratio (o/e) 1, 90% interval 0.79 to 1.28.
Homologues: Orthologues: macaque CCDC28A (100% identical), chimpanzee CCDC28A (99% identical), guinea pig CCDC28A (98% identical), dog CCDC28A (95% identical), rabbit CCDC28A (95% identical), mouse Ccdc28a (93% identical), pig CCDC28A (89% identical), rat Ccdc28a (84% identical), tropical clawed frog ccdc28a (71% identical), zebrafish ccdc28a (62% identical), Drosophila melanogaster CG10874 (38% identical). Paralogues in human: CCDC28B (53% identical).
Diseases named in the same sentence as CCDC28A in open-access papers:
CCDC28A is named in the same sentence as 7 diseases in open-access papers, as found by Europe PMC text mining. Sharing a sentence is not in itself a finding about the gene and the disease. The quoted sentences say what the papers report.
glioma (2 papers, 2020 to 2023). A benign or malignant brain and spinal cord tumor that arises from glial cells (astrocytes, oligodendrocytes, ependymal cells). "Proteins NOL4 (a cancer-testis antigen) and KALRN showed an antigenic response in the CSF of GBM patients, whereas, UTP4 and CCDC28A showed an antigenic response in low grade gliomas when compared with the control samples." (PMID 33415070, 2020). "In a comparison of low-grade glioma and control, 2 proteins viz., U3 small nucleolar RNA-associated protein 4 homolog (UTP4) and Coiled-Coil domain containing 28A (CCDC28A) showed a significant response." (PMID 33415070, 2020). "The expression of the CCDC28A gene changes in low-grade and high-grade gliomas, which may be related to the development of these diseases." (PMID 37664112, 2023).
male infertility (2 papers, 2024). The inability of the male to effect fertilization of an ovum after a specified period of unprotected intercourse. "Future studies exploring the molecular mechanisms underlying CCDC28A function and its interactions with other proteins involved in sperm tail formation and motility will provide further insights into male infertility and potential therapeutic targets for reproductive disorders." (PMID 39500989, 2024). "Altogether, our results reveal the essential role of CCDC28A in regulating sperm morphology and motility and suggesting a potential marker for male infertility." (PMID 38597936, 2024). "Here we demonstrated that CCDC28A, a member of the CCDC family proteins, is highly expressed in testes and the CCDC28A deletion leads to male infertility." (PMID 38597936, 2024). "Overall, we found that loss of CCDC28A can lead to male infertility and that ICSI can overcome the infertile phenotype of Ccdc28a–/– mice." (PMID 38597936, 2024). "Through knockout mouse models and histological analyses, we reveal that CCDC28A deficiency results in diminished sperm motility and structural aberrations in sperm tails, notably affecting the head-tail coupling apparatus (HTCA), thereby causing male infertility." (PMID 39500989, 2024).
colon cancer (1 paper, 2023). "A recent study also found that the CCDC28A gene is a significant prognostic marker for patients with colon cancer." (PMID 37664112, 2023).
cyst (1 paper, 2025). A sac-like closed membranous structure that may be empty or contain fluid or amorphous material. "In support of selective sharing, recent work in mouse testes showed that certain mRNAs are always shared between sister cells in cyst (e.g., Sycp3), others are only partially shared (e.g., Ccdc28a), and some are never shared (e.g., Smok2b)." (PMID 41213017, 2025).
Infertility (1 paper, 2024). "It has been reported that disruption of SPACA1 leads to infertility due to abnormal sperm head shape and abnormal acrosomes in sperm, and GSK3A-deficient mice show bent sperm heads, similar to the phenotype of Ccdc28a−/− mice." (PMID 38597936, 2024).
microcephaly (1 paper, 2024). A congenital or acquired developmental disorder in which the circumference of the head is smaller than normal for the person's age and sex. "Scanning electron microscopy further confirmed that the sperm from the Ccdc28a–/– mice showed obvious sperm head defects including bent heads, microcephaly, and irregular shapes, while the sperm flagellum from both Ccdc28a+/+ and Ccdc28a–/– mice had normal morphology." (PMID 38597936, 2024).
T cell acute lymphoblastic leukaemia (1 paper, 2020). "CCDC28A encodes for coiled-coil domain containing protein and is a known translocation partner of nucleoporin 98 (NUP98) in T cell acute lymphoblastic leukaemia (T-ALL)." (PMID 33415070, 2020).